ORM1 (orosomucoid 1)
Description:
Functions as a transport protein in the blood stream. Binds various ligands in the interior of its beta-barrel domain. Also binds synthetic drugs and influences their distribution and availability in the body. Appears to function in modulating the activity of the immune system during the acute-phase reaction.
Synonyms: AGP1; A1AG1; AGP-A; HEL-S-153w; ORM
Tractability: Small molecule: a structure with a bound ligand is known; it has a high-quality binding pocket. Antibody: its Gene Ontology location is reachable by antibodies, with high confidence; UniProt places it where antibodies can reach, with medium confidence; UniProt predicts a signal peptide or a membrane-spanning region.
Target class: Secreted protein
Gene: Protein-coding gene on chromosome 9 (114,323,025 to 114,326,479, forward strand). Ensembl gene ENSG00000229314.
Subcellular location: Secreted
Subcellular location (Human Protein Atlas): Vesicles; Golgi apparatus; Predicted to be secreted
Pathways (Reactome):
Hemostasis: Platelet degranulation
Immune System: Neutrophil degranulation
Gene Ontology:
Molecular function: protein binding; molecular carrier activity
Biological process: negative regulation of interleukin-6 production; negative regulation of tumor necrosis factor production; positive regulation of interleukin-1 beta production; positive regulation of interleukin-1 production; positive regulation of tumor necrosis factor production; acute inflammatory response to antigenic stimulus; acute-phase response; inflammatory response; regulation of immune system process
Cellular component: blood microparticle; extracellular exosome; extracellular region; platelet alpha granule lumen; specific granule lumen; tertiary granule lumen
Genetic constraint (gnomAD): Loss-of-function variants: 13 observed, 20.68 expected, observed/expected ratio (o/e) 0.63, 90% interval 0.41 to 1. The upper end of that interval is the gene's LOEUF score, 1, which puts it in group 4 of 6, group 1 being the genes least tolerant of losing a copy. Missense variants: 175 observed, 178.07 expected, observed/expected ratio (o/e) 0.98, 90% interval 0.87 to 1.11. Synonymous variants: 63 observed, 62.97 expected, observed/expected ratio (o/e) 1, 90% interval 0.82 to 1.23.
Homologues: Orthologues: macaque ORM1 (84% identical), rabbit ORM1 (58% identical), rat Orm1 (50% identical), mouse Orm1 (50% identical), mouse Orm2 (46% identical), mouse Orm3 (45% identical), zebrafish apom (17% identical). Paralogues in human: ORM2 (90% identical).
Diseases named in the same sentence as ORM1 in open-access papers:
ORM1 is named in the same sentence as 141 diseases in open-access papers, as found by Europe PMC text mining. Sharing a sentence is not in itself a finding about the gene and the disease. The quoted sentences say what the papers report.
COVID-19 (15 papers, 2022 to 2025). A disease caused by infection with severe acute respiratory syndrome coronavirus 2. "We found that the expression levels of inflammation-related proteins (CRP, SAA1, SAA2, and ORM1) were substantially elevated in the acute phase of COVID-19, consistent with the proteomic results." (PMID 38965561, 2024). "By searching for DTGs associated with IRGs shared between COVID-19 and IS, we identified eight DEGs interacting with two known databases of drug targets: JAK2, ORM1, RNASE2, TNFSF13B, CYBB, EIF2AK2, CD79B and CAMP." (PMID 36969251, 2023). "Many of these proteins, such as SERPINA3, ORM1 and ORM2, have been used to distinguish between mild and severe cases of COVID-19." (PMID 38965561, 2024). "COVID-19 patients produced greater ORM-1, alpha-1-antitrypsin, and haptoglobin acute phase proteins compared to both COVID-19 negative and healthy control patients." (PMID 38786270, 2024). "In line with the cytokine storm hypothesis, several acute phase proteins were elevated in serum of COVID-19 patients, such as CRP, Lipopolysaccharide Binding Protein (LBP), ORM1, and ORM2." (PMID 37739942, 2023). "Traditionally, CRP has been used as a systemic clinical marker of inflammation in COVID-19 and other diseases, although the SROC curves suggest that other acute phase proteins, such as ORM1, CRTAC1, SERPINA3, TF, and AHSG might perform better as biomarkers of inflammation." (PMID 37739942, 2023). "Cluster 12 and 13 report proteins that are increased in all COVID-19 patients but at higher levels in ICU/F patients which are mainly constituted by proteins playing a role in acute inflammatory response (CRP, ORM1, ORM2, SAA1, SAA2, S100A8, S100A9, Serpin A3)." (PMID 36348270, 2022).
breast carcinoma (11 papers, 2019 to 2025). "Taken together, ORM1 is associated with increased proliferation, migration, and epirubicin resistance of breast cancer." (PMID 34654351, 2021). "In this study, we evaluated ORM1 expression in epirubicin-resistant breast cancer cells and determined the underlying mechanism of action of ORM1." (PMID 34654351, 2021). "Thus far, the data from this study indicate that ORM1 may promote the malignant phenotype of breast cancer cells, so we further analyzed the underlying mechanism by western blot analysis." (PMID 34654351, 2021). "For example, elevated ORM1 levels seen in patients with breast cancer leads to tumorigenesis and epirubicin resistance." (PMID 37640741, 2023). "Taken together, ORM1 restores the migration ability of breast cancer cells by targeting MMP-2 and MMP-9." (PMID 34654351, 2021). "The upregulated expression of ORM1 in breast cancer cells was consistent with data from the reanalysis of the GSE58812 dataset." (PMID 34654351, 2021). "We collected 10 pairs of breast cancer specimens along with corresponding adjacent normal tissues from the pathology department of Hengyang Central hospital, and the expression of ORM1 was measured by IHC and qRT-PCR." (PMID 34654351, 2021). "ORM1 has been shown to play an important role in chemotherapeutic drug resistance in breast cancer cells." (PMID 34654351, 2021). "In summary, ORM1 promotes the malignant phenotype of breast cancer by upregulating the expression of MMP-2 and MMP-9." (PMID 34654351, 2021). "Taken together, the expression of ORM1 was upregulated both in breast cancer tissues and cell lines, which included an epirubicin-resistant cell line." (PMID 34654351, 2021). "Taken together, we demonstrated that ORM1 promotes the malignant phenotype of breast cancer by upregulating the expression of MMP-2 and MMP-9, thus activating the AKT/ERK signaling pathway." (PMID 34654351, 2021). "Our study shows that ORM1 is increased, not only in breast cancer cells, but also in an epirubicin-resistant cell line." (PMID 34654351, 2021). "Taken together, downregulation of ORM1 suppresses the malignant phenotype and increases the drug sensitivity of epirubicin-resistant breast cancer cells." (PMID 34654351, 2021). "Downregulating the expression of ORM1 reversed the malignant phenotype of breast cancer cells by targeting MMP-2 and MMP-9 and activating the AKT/ERK signaling pathway." (PMID 34654351, 2021). "Taken together, our results indicate that upregulation of ORM1 increases epirubicin resistance in breast cancer cells in vitro." (PMID 34654351, 2021). "In the present study, the data revealed that when compared with normal breast tissue and cell lines, the expression of ORM1 was upregulated in breast cancer tissues and cell lines." (PMID 34654351, 2021). "In the present study, we found that ORM1 not only enhanced the proliferation and migration, but also epirubicin resistance of breast cancer cells." (PMID 34654351, 2021). "This contrasts with reports suggesting that elevated ORM1 expression correlates with chemotherapy resistance and increased metastasis in certain solid tumors, such as breast cancer and hepatocellular carcinoma, highlighting how the role of a protein can vary across different malignancies." (PMID 40299486, 2025). "We found that the expression of ORM1 was upregulated in breast cancer tissues and cell lines." (PMID 34654351, 2021). "We measured the expression of ORM1 in breast cancer tissues and cell lines using qRT-PCR." (PMID 34654351, 2021). "Moreover, the upregulation of ORM1 not only enhanced the proliferation, but also the migration of breast cancer cells." (PMID 34654351, 2021). "Orosomucoid 1 (ORM1) has been shown to be upregulated in the serum of breast cancer patients; however, the expression and function of ORM1 in breast cancer remains unknown." (PMID 34654351, 2021).
breast carcinoma (continued). "Moreover, compared with the normal breast cell line HBL-100, the expression of ORM1 was increased in the MDA-MB-231 breast cancer cell line and the epirubicin-resistant MDA-MB-231/EPI cell line." (PMID 34654351, 2021). "Therefore, ORM1 may represent a potential therapeutic target for breast cancer and promote epirubicin resistance by regulating the expression of MMP-2 and MMP-9, as well as activating the AKT/ERK signaling pathway." (PMID 34654351, 2021). "Orosomucoid 1 (ORM1) upregulates the expression of matrix metalloproteinases (MMP-2 and MMP-9) consequently promoting epirubicin resistance in breast cancer." (PMID 36699376, 2022). "However, the function of ORM1 in breast cancer remains unknown." (PMID 34654351, 2021).
hepatocellular carcinoma (9 papers, 2016 to 2025). A malignant tumor that arises from hepatocytes. "The representative gene of C10 (LIHC) is ORM1, which is considered as a prognostic biomarker for hepatocellular carcinoma." (PMID 33166290, 2020). "ORM1 is an acute-phase protein, and increased ORM1 levels have been reported in the serum of patients with various malignant diseases, including hepatocellular carcinoma, gynecological carcinomas, esophageal cancer and head and neck cancers." (PMID 27386438, 2016). "In hepatocellular carcinoma (HCC), ORM1 was highly correlated with tumor grade and vascular invasion." (PMID 37735575, 2023). "This study aimed to clarify the role of Orosomucoid 1 (ORM1) in the development and therapy resistance in hepatocellular carcinoma (HCC)." (PMID 35765957, 2022).
Obesity (8 papers, 2016 to 2026). Accumulation of substantial excess body fat. "Adipose tissue expression of ORM1 or the actions of hepatic secreted ORM1 within adipose tissue may be of importance due to the association of APPs with metabolic syndrome and insulin resistance in animal models of obesity." (PMID 27087941, 2016). "A genome-wide association study suggests that ORM1 mediates the link between obesity and MASLD and impacts MASLD independently of obesity." (PMID 40243151, 2025). "Other studies have linked obesity and weight change with CRP, APCS, ADIPOQ, C3 and other complement proteins, ORM1, and ORM222,34,36–38." (PMID 37794065, 2023). "The expression reduction of Lep and Orm1 in H5% mice implied the remission of obesity and metabolic syndrome." (PMID 34760253, 2021). "Alpha‐1‐acid glycoprotein 1 (ORM1) was upregulated in our patients with severe obesity." (PMID 41077621, 2026). "Moreover, a recent study reported that the administration of ORM1 ameliorated obesity and exerted a direct anti-fibrosis effect in adipose tissue via AMPK activation." (PMID 35741222, 2022). "Thus, the upregulation of ORM1 in our patient population with obesity may represent a compensatory mechanism to prevent harmful effects of excess inflammation." (PMID 41077621, 2026). "ORM1 was significantly elevated in sera, liver, and adipose tissues from mice with high-fat-diet (HFD)-induced obesity and could function through leptin receptors to regulate food intake and energy homeostasis in response to nutrition status." (PMID 35741222, 2022). "Some classical inflammatory biomarkers, including CRP, SAA1, ORM1, and LBP, were determined to further confirm the notably lower inflammatory responses of IBD patients with overweight/obesity than those without overweight/obesity." (PMID 36759757, 2023).
lung carcinoma (7 papers, 2013 to 2025). "Although the precise role of ORM1 in lung development is not well understood, it has been identified as a biomarker for lung cancer, and has been shown to enhance cell proliferation." (PMID 39417930, 2025). "There was a strong correlation between the survival time of individuals with lung cancer and 7 genes (CLEC3B, AOC3, HBB, CAT, SEPP1, FGA, and ORM1, P<0.05)." (PMID 40496615, 2025).
bladder cancer (6 papers, 2012 to 2025). "Other studies have also noted the prognostic and predictive value of ORM1 in cancer diagnosis and treatment for several other cancers, including ovarian and bladder cancers." (PMID 35765957, 2022). "Fei and colleagues quantified ORM1 protein in urine samples of 186 bladder cancer patients and found that urinary ORM1-Cr was higher in bladder cancer patients compared to controls (p < 0.0001)." (PMID 30544619, 2018). "They suggest that increased level of urinary ORM1 protein might be a useful biomarker for bladder cancer diagnosis." (PMID 30544619, 2018). "Interestingly, the same strategies allowed the identification of increased levels of ORM1 in urine samples of patients with urinary bladder cancer." (PMID 22888844, 2012).
Sepsis (6 papers, 2016 to 2026). Sepsis is defined as life-threatening organ dysfunction caused by a dysregulated host response to infection. "SAA3, CXCL9, and Orm1 are induced by pulmonary inflammation, while Pon1 is associated with oxidative stress in sepsis caused by MRSA (40, –, 43)." (PMID 38323827, 2024). "Genes encoding members of the acute phase protein response, C-reactive protein (Crp), and orosomucoid 1 and 2 (Orm1, Orm2) belong to the group of genes upregulated by sepsis in both organs." (PMID 37638006, 2023).
ischemic stroke (5 papers, 2019 to 2025). A stroke disorder caused by obstruction of blood flow to the brain, due to thrombotic (local blood clot formation) or embolic (due to a blood clot or other material traveling from another site) event. "Increased expression of ORM1 after cerebral ischemia exacerbates the disruption of the BBB after ischemic stroke, and may also contribute to thrombotic susceptibility through an immunothrombotic mechanism." (PMID 36959823, 2023). "Orosomucoid 1 (ORM1), an acute-phase protein, plays important roles in inflammation and ischemic stroke; however, the roles and mechanisms of ORM1 in DOX-induced cardiotoxicity remain unknown." (PMID 33134382, 2020).
prostate carcinoma (5 papers, 2012 to 2025). A carcinoma that arises from epithelial cells of the prostate gland. "Downregulation of PAH and AOC1 and upregulation of DDC, LIN01436, and ORM1 were associated with the development of prostate cancer." (PMID 36497304, 2022). "Similar to F3 and CREB3L1, the upregulation of ORM1 (by 174.684-fold) indicated that the progression of prostate cancer in LNCaP xenograft tumor might be driven by an inflammatory tumor microenvironment." (PMID 33808801, 2021). "We analyzed 14 additional genes, including the AR-activated genes PSA, FKBP51, ORM1, STAG, Nkx3.1, FASN, AQP3, KLK2, and UGT2B; the AR-repressed genes DKK and FST; and the castration-resistant prostate cancer AR-regulated genes CDC20, CDK1, and UBE2C." (PMID 22761715, 2012).
colorectal cancer (4 papers, 2009 to 2024). A primary or metastatic malignant neoplasm that affects the colon or rectum. "ORM1 has also been shown to be responsive to acute inflammation and is linked to immunosuppression in colorectal cancer through Macrophage M2 polarization." (PMID 38201640, 2024). "Furthermore, in colorectal cancer, ORM1 is believed to be a hub gene associated with CRLM15." (PMID 37640741, 2023). "log(P/(1-P) = -7.8709 + 4.5956 × IGFBP2 + 0.2732 × ITIH3 + 0.0909 × LRG1 + 0.1015 × C9 -3.2205 × CNDP1 + 0.0239 × ORM1 + 0.0811 × SERPINA1, where P is a value between 0 and 1 that represents the probability of the event (colorectal cancer)." (PMID 38383428, 2024).
atherosclerosis (3 papers, 2014 to 2022). A disease characterized by the build-up of fatty material and calcium deposition in the arterial wall resulting in partial or complete occlusion of the arterial lumen. "Three cardiovascular signaling pathways identified by IPA software including “Atherosclerosis Signaling” (related gene: ORM1, ORM2, and S100A8)." (PMID 36277748, 2022). "In addition to cytokine and chemokines genes the “Atherosclerosis Signalling” and “Communication between Innate and Adaptive Immune cells” pathways had CD40, ICAM1, ORM1 and ORM2 as being significantly expressed within the pathways at 1 hour following LPS and Pam3CSK4 stimulation." (PMID 24842522, 2014).
cervical cancer (3 papers, 2016 to 2023). A primary or metastatic malignant neoplasm involving the cervix. "The high expression of ORM1 is related to lymph node metastasis and the clinical stage of cervical cancer patients as well as the poor prognosis." (PMID 36498728, 2022). "The high expression of ORM1 is related to lymph node metastasis and clinical stage of cervical cancer patients as well as the prognosis, which is undoubtedly an important supplement to SCC-Ag." (PMID 36498728, 2022). "The grey module of 431 proteins was also weakly correlated with the cervical cancer stage, and a series of core proteins such as ORM1 and QOSX1, represented the hub protein." (PMID 36498728, 2022). "We performed Chi-square test and Kaplan–Meier analysis in the cervical cancer patients, to explore the relationship between ORM1/APOF expression and the clinicopathological factors as well as the survival prognosis." (PMID 36498728, 2022). "By validating the hub proteins using the ELISA, the authors introduced ORM1 (Orosomucoid 1) and APOF (Apolipoprotein F) as novel potential plasma markers in high grade squamous intraepithelial lesion (HSIL) and cervical cancer." (PMID 38328436, 2023). "The results revealed that the plasma expression level of ORM1 has the highest expression in HSIL, followed by cervical cancer, and the lowest expression in healthy volunteers (1092 ± 7.3 vs. 952.2 ± 6.9 vs. 859.2 ± 7.4 ng/mL, p < 0.001)." (PMID 36498728, 2022). "Western blot analysis confirmed that LYZ, ORM1, LYN, STMN1 significantly increased in cervical cancer, while LUM, BGN, KRT4 significantly decreased." (PMID 27690342, 2016). "Its function includes modulating immunity, binding and carrying drugs, maintaining the barrier function of capillary, and mediating the sphingolipid metabolism, but no study was found for ORM1 in cervical cancer." (PMID 36498728, 2022). "However, when we defined the top 20% expression as high expression and the remaining 80% as low expression, the ORM1 was related with the PFS and OS of these cervical cancer patients." (PMID 36498728, 2022). "By validating the hub proteins using the ELISA, we found that ORM1 and APOF could be the new potential plasma biomarkers in HSIL and cervical cancer, and further functional studies are worth exploring." (PMID 36498728, 2022). "We found that LYZ, ORM1, LYN and STMN1 significantly increased in cervical cancer samples." (PMID 27690342, 2016). "We found that the expression level of ORM1 in cervical cancer tissues was not correlated with age, histology, tumor differentiation, clinical stage, tumor size, LVSI or deep stromal invasion (DSI), but was related to lymph node metastasis (LN) and clinical stage." (PMID 36498728, 2022). "ORM1 with or without APOF has high sensitivity and specificity in diagnosing HSIL and cervical cancer." (PMID 36498728, 2022).
colon cancer (3 papers, 2012 to 2023). "In summation, these results demonstrated that ORM1 induces malignant phenotypes in colon cancer cells by affecting PI3K/AKT signaling pathway." (PMID 37640741, 2023). "Hence, it was concluded that high levels of ORM1 promoted the proliferative, migratory, and invasive activities of colon cancer cells." (PMID 37640741, 2023). "Alternatively, the high expression of ORM1 in OM could represent a defense mechanism against proliferation and invasion of the tumor cells, similar to what occurs in colon cancer cells." (PMID 22888844, 2012). "Compared with that in non-metastatic colon cancer cell HCT116, moderately or highly metastatic colon cancer cells, SW480 or Lovo, highly expressed ORM1." (PMID 37640741, 2023).